CCDC196 (coiled-coil domain containing 196)
Synonyms: C14orf53; LINC00238; NCRNA00238
Gene: Protein-coding gene on chromosome 14 (66,411,704 to 66,498,677, forward strand). Ensembl gene ENSG00000196553.
Homologues: Orthologues: chimpanzee CCDC196 (98% identical), macaque CCDC196 (95% identical), rabbit CCDC196 (84% identical), pig CCDC196 (78% identical), guinea pig CCDC196 (66% identical), mouse Ccdc196 (65% identical), rat Ccdc196 (42% identical).
Diseases named in the same sentence as CCDC196 in open-access papers:
CCDC196 is named in the same sentence as 2 diseases in open-access papers, as found by Europe PMC text mining. Sharing a sentence is not in itself a finding about the gene and the disease.
CCDC196 shares sentences with these, for which no sentence is quoted: liver cancer (1 paper); tumor (1).